IL1B (interleukin 1 beta)
Diseases named in the same sentence as IL1B in open-access papers (continued):
Sharing a sentence is not in itself a finding about the gene and the disease.
tumor (continued). "Compared to control tumor cells, the IL-1β-stimulated tumor cells possessed enhanced sphere formation ability." (PMID 32547321, 2020). "The inflammasome controls the production of IL-1β and IL-18 and both cytokines are involved in tumor development or control." (PMID 33042810, 2020). "Further, 5-FU activates the inflammasome in dying MDSCs leading to IL-1β secretion and IL-17 production by Th17 cells that increased angiogenesis and stimulated tumor growth." (PMID 32575843, 2020). "On the contrary, tumor-derived gPTGS2 was defined in cases with low + high or high + low gPTGS2 and IL1β levels (= independence of IL1β and gPTGS2 expression)." (PMID 32168749, 2020). "Knockdown of IL-1β decreased tumor growth and reversed TAM immune suppression while increasing the frequency of polyclonal CD8 T cells and their production of IFNγ and Granzyme B." (PMID 33584701, 2020). "Through IHC experiments, we found that CD44s, NLRP3, caspase-1, and IL1B were expressed in most tumor cells, and we demonstrated the positive relationship between CD44s and caspase-1 by quantifying IHC results." (PMID 33168816, 2020). "Tumor-derived IL-1β induces γδ T cells to produce IL-17A and granulocyte-colony stimulating factor (G-CSF), which results in the recruitment of immunosuppressive neutrophils to the lung." (PMID 32849639, 2020). "Inhibition of IL-1β by anakinra suppressed tumor metastasis in the head and neck region as well as in LN and even reduced the growth of the mammary primary tumor in the early stages of disease progression." (PMID 31685946, 2020). "Low levels of IL-1β, TNF-α, and IL-6 stimulate angiogenesis, and IL-6 modulates polarization of tumor-associated macrophages (TAM) from M1 (a tumor-eliminating phenotype) to M2 (an anti-inflammatory and tumor-promoting phenotype)." (PMID 33195486, 2020). "One study also noted an increased expression of IL-1β and E-selectin in premetastatic lungs in mice with melanoma, prior to the arrival of tumor cells." (PMID 33322216, 2020). "Several key cytokines, such as TNF-α and interleukin-1β (IL1β), stimulate inflammatory programs that coordinate functions of tumor-infiltrating leukocytes (TILs) and their presence in the tumor milieu via a plethora of proinflammatory chemokines." (PMID 33322099, 2020). "Consistently, the secretion of pro‐inflammatory cytokines, such as IL‐1β, by colon explants as well as mRNA levels of several pro‐inflammatory genes in the tumor tissue were significantly decreased following aspirin administration." (PMID 31994315, 2020). "The consequences of high IL-1β expression are a decrease in functional natural killer (NK) cells and increased tumor growth." (PMID 32635472, 2020). "We further evaluated the possibility of IL‐1β in inducing endothelial cell apoptosis that occurs in the late phase of extravasation of tumor cells, because IL‐1β is known to promote cell death." (PMID 33252861, 2020). "In the mammary 4T1 tumor model, overexpression of IL-1β (in the tumor or the host) or the invalidation of IL-1RA led to an accumulation of Ly6C negative MDSCs, that is, polymorphonuclear (PMN)-MDSCs, whereas blocking IL-1β decreases the number of MDSCs." (PMID 32635472, 2020). "The ability of IL-1β in inducing angiogenic pathways, which trigger tumor progression, has been widely reported, although the mechanisms through which this event occurs have not been completely defined." (PMID 32796686, 2020). "In the PDAC microenvironment, proinflammatory cytokines secreted by tumor cells and infiltrating immune cells, such as interleukin (IL)-1β, IL-6, and tumor necrosis factor (TNF)-α, have been shown to modulate PDAC progression and immune evasion." (PMID 32929072, 2020). "It is suggested that the primary tumour encourages metastasis by induction of systemic inflammation via IL-1B, which leads to the expression of IL-17 from γδ T cells." (PMID 32076063, 2020).
tumor (continued). "Consistently, our subsequent experiments proved that tumor cells secret IL1β to activate the NF-κB pathway in SCs." (PMID 32308766, 2020). "A limit of this study is that the systemic IL-17 levels were not directly analyzed and the authors instead showed the Th17 cells differentiation-related cytokines IL-23, IL-1β, and IL-6 in the local tumor tissue." (PMID 32298379, 2020). "Many studies have showed that proinflammatory cytokines, such as MCP-1, IL-1B, and IL-6, induce angiogenesis and promote tumor growth, invasion and metastasis." (PMID 32548715, 2020). "With regard to plasma chemokine levels, IL-1β was increased in females and IL-10 was increased in males, more markedly in the males with tumor." (PMID 32545680, 2020). "The IL-1β responsible for migration/invasion was shown to be produced by cells in the tumor microenvironment, such as macrophages, fibroblasts, and B-cells." (PMID 32635472, 2020). "IL‐1β can up‐regulate VEGF expression in tumour cells and augment angiopoietin‐1 expression in human endothelial cells." (PMID 32239650, 2020). "In this study, we were able to detect an increased release of the proinflammatory cytokines IL-1β and IL-6 from tumor cells treated with the highly cytotoxic NB-PDT." (PMID 32326519, 2020). "The migration of immune cells to tumor environment is the first step to exert their effects, therefore we selected the genes related to leukocyte migration, including IL-1β, ITGA4, ITGB2, ITGB7, CAV1, and MAG." (PMID 32358484, 2020). "Overexpression of IL-1β in mammary 4T1 tumor cells can modify MDSC phenotype (more CD8, CD80, CD83, and CD14 expression and lower CD44 and B220) in vivo, while it does not change their capacity to dampen CD4 and CD8 T-cells’ activation/proliferation." (PMID 32635472, 2020). "In the context of tumor, IL-1β appears to be the most important inflammatory mediator at the level of the hypothalamus and glucocorticoids are essential for the effects on protein degradation at the level of the muscle." (PMID 33291708, 2020). "Results of this research show that blocking IL-1β activity using an IL-1β antibody abolished the anti-tumor effects of S.t-ΔpGlux/pT-ClyA." (PMID 31754923, 2019). "Noteworthy, EL4 tumor-mice fed a DHA diet for 7 days prior to 5-FU injection showed a decrease in plasma IL-1β level compared to 5-FU-injected mice fed a standard diet." (PMID 31217433, 2019). "We therefore set out to elucidate the mechanism by which CAF-derived IL-1β at the primary tumour site enhances metastases formation." (PMID 31558756, 2019). "Exogenous injection of IL-1β resulted in tumor regression, as long as the tumors were of a sufficient size, and the mice were not deficient in T cells." (PMID 31231372, 2019). "We demonstrated that highly purified DHA enhances 5-FU anti-tumor efficacy in a murine cancer model, by repressing 5-FU-induced IL-1β secretion in MDSC under the control of NLRP3 inflammasome and JNK pathway through β-arrestin-2." (PMID 31217433, 2019). "The cytokines secreted by tumor cells, such as granulocyte colony-stimulating factor (G-CSF), interleukin (IL)1β, IL6 or tumor necrosis factor (TNF), have been suggested to extend their lifespan." (PMID 31408948, 2019). "IL-1β has a role in tumor progression via induction of several tumor growth factors and of endothelial-mesenchymal transition." (PMID 31049358, 2019). "Under both experimental conditions, disrupting endothelial ICAM-1/tumor LFA-1 interaction results in a dramatic reduction in the secretion of IL-1β, IL-6, PGE2 and TNFα into the co-culture supernatant." (PMID 31511625, 2019). "IL-1β, one of the inflammatory cytokines released from myeloid cells in tumor microenvironment, plays an important role in development and progress of tumor." (PMID 31439870, 2019). "We have preliminary data showing that tumour cell-conditioned medium induces IL1β production by the bone marrow." (PMID 31676788, 2019).
tumor (continued). "MEK-I modulates in–vitro the immune micro-environment through a transcriptionally decrease of PD-L1 expression, enhance of MHC-I expression on tumor cells, increase of the production of several cytokines, like IFNγ, IL-6, IL-1β and TNFα." (PMID 31196138, 2019). "For instance, IL-37 reduces the secretion by both immune cells and tumor cells of IL-6, IL-1β and tumor necrosis factor alpha, cytokines known to play a role in tumor progression." (PMID 31231372, 2019). "More importantly, the pro-inflammatory cytokine IL-1β has significant effects on tumor growth, invasiveness and metastasis." (PMID 31492049, 2019). "Using cytokine array platform, we found that in the tumor microenvironment the immune cells, in particular monocytes/macrophages, are the most significant sources of IL1β when compared with fibroblasts." (PMID 31419632, 2019). "Previous research reported tumor recurrence after treatment, which was related to decreased IL-1β levels." (PMID 31754923, 2019). "Numerous reports have indicated that IL-1β is produced during inflammation, and this cytokine stimulates tumor cell proliferation and promotes angiogenesis and tumor invasion." (PMID 31139563, 2019). "In contrast to IL‐1α and IL‐1β, which promote tumor progression through inflammation, IL‐1RA possesses a tumor‐suppressing effect by blocking the binding of IL‐1 to its target receptor." (PMID 31102307, 2019). "Our results demonstrate that suppression of ATP-induced NLRP3 inflammasome activation and IL-1β secretion in tumor microenvironment, contributes to decreasing metastatic potential of cancer cells." (PMID 31439870, 2019). "In a recent publication, we showed that IL-1β secreted by IRISOE TNBC tumor cells within the aggressiveness niche recruited MSCs to the aggressiveness niche and initiated strong bi-directional interactions with them that led to CXCL1 secretion from MSCs." (PMID 31014367, 2019). "Herein we show that administration of IL-1β markedly improved the efficacy of adoptively transferred T cells in mediating tumor regression by increasing their cell numbers and functionality within the tumor." (PMID 31405895, 2019). "In fact, in the presence of low local doses, IL-1β induces an efficient anti-tumour immunity and suppresses tumour formation, whereas in the presence of high local doses, IL-1β is positively related to all the phases of malignancy." (PMID 31480312, 2019). "Two transcripts, the cytokines Il1b and Ifna, were more elevated in tumor-bearing animals treated with R848 as compared with vehicle alone (P < 0.0001 and P < 0.01, respectively, analysis of variance (ANOVA) with Tukey’s test)." (PMID 31615993, 2019). "We found that IL-1β treatment increased Pmel-1 cell numbers only in the tumor but enhanced Gzm B expression in both the tumor-draining LNs and tumor, consistent with the OT-I findings." (PMID 31405895, 2019). "Our study adds further weight for a promoting role of IL1β in metastasis, and challenges the assumption that IL1β is tumour derived." (PMID 31676788, 2019). "SW480- and U87-MG-derived exosomes induce the release of IL-1α, IL-8 and MCP-1 by monocytes, while exosomes released from all tumor cell lines after LPS treatment trigger the production of IL1β, IL-10, IL-6, MIP-1α, MIP-1β and TNF-α cytokines." (PMID 31186484, 2019). "An increase in plasma and tumor ANGPTL-4 was detected in cancer cachexia patient, as well as an association to proinflammatory factors such as NFκB, IL-1β and MCP-1." (PMID 31741709, 2019). "Inflammasome activation and subsequent production of IL-1β has also been shown to enhance tumour invasiveness, growth and metastasis." (PMID 31438559, 2019). "IL-1β was previously shown to promote tumour cell invasion and metastasis by modulating the expression of matrix metalloproteinases in cancer cells, specifically MMP1, MMP3, and MMP1045." (PMID 31558756, 2019).
tumor (continued). "Recent studies have shown that obesity can increase the infiltration of tumor-related macrophages, upregulate the production of IL-1β, and promote angiogenesis and tumor progression." (PMID 31440472, 2019). "While IL-1β is a pluripotent cytokine and plays a role in tumorigenesis and tumor progression, the role of IL-1β in radiation-induced normal tissue toxicity is unclear but has been related to skin-related adverse events." (PMID 32010614, 2019). "We next sought to investigate the functional role of CAF-derived NLRP3/IL-1β pathway in tumour growth in vivo." (PMID 31558756, 2019). "Haabeth and colleagues also demonstrated that IL-1β drives activation of tumor specific Th1 responses, thus protecting against B cell myeloma and lymphoma." (PMID 31231372, 2019). "It has long been known that in mice, inflammasome activation and IL-1β accelerate tumor invasiveness, growth, and metastatic spread." (PMID 30767158, 2019). "The knockdown of CEBPD in U373MG and T98G cells significantly reduced the area and number of tumor spheroids after IL-1β treatment." (PMID 31300060, 2019). "Taken together, this study has shown for the first time that astrocytes produce more TGF-β2 in response to tumor cell-derived IL-1β and TNF-α." (PMID 31602400, 2019). "In vivo, TAMs from KEP tumors of CCL2-blocking antibody-treated mice showed significantly decreased IL-1β mRNA expression vs. control KEP tumor-bearing mice." (PMID 31921102, 2019). "Multiple types of cell, including tumor cells and stromal cells, can produce and release IL-1β and IL-18 into the tumor microenvironment." (PMID 31492049, 2019). "It was possible that IL-1β elicits downstream molecules possessing anti-tumor activities to modulate its function in RCC." (PMID 31816951, 2019). "Our data indicate that the paracrine signaling between the ER+BCC and fibroblasts cooperates with the CD45+CD31+ cells in the tumor microenvironment to create an IL1β-enriched niche that augments tumor cell proliferation." (PMID 31419632, 2019). "Cytokines, such as tumor necrosis α (TNF-α), interleukin 1β (IL-1β), and interleukin 6 (IL-6), are also shown to correlate with tumor-promoting inflammation." (PMID 31380247, 2019). "Using the regression analysis we verified, in CC group, that ANGPL-4 content in the tumor was associated positively with IL-1β and MCP-1 contents; in the mesenteric adipose tissue with IL-1β content, and ANGPTL-4 plasma level with NFκB content in tumor." (PMID 31741709, 2019). "Given the importance of IL-1β-mediated intracellular signaling, our study first focused on berberine as a key modulator of tumor microenvironment by targeting IL-1β." (PMID 31139563, 2019). "Contrasting tumor-inhibiting effects have also been ascribed to IL-1β in the case of colorectal cancer (CRC)." (PMID 31231372, 2019). "Based on our findings at the mRNA levels, it is possible that DLL1, whose expression was elevated in MSCs by TNFα and IL-1β stimulation (through a p65-mediated pathway, as analyzed for TNFα stimulation), is a partner of tumor cell-expressed Notch1." (PMID 31105691, 2019). "IL‐1α and IL‐1β bind to the same receptor and perform similar biological activities, such as promoting tumor growth and metastasis via enhanced angiogenesis." (PMID 31102307, 2019). "On the other hand, in some instances, tumor cells can inhibit the PDGF-BB and IL-1β production by MSCs, which in turn reduces the angiogenesis and tumor growth." (PMID 31827403, 2019). "This study aimed to prove that YAP1 plays a tumor‐promoting role in Hp‐induced gastric carcinogenesis via activating the key cancer‐related inflammatory cytokine IL‐1β and thereby provide a new drug target for GC treatment." (PMID 31145543, 2019). "We demonstrate here that the administration of IL-1β can potentiate the efficacy of adoptively transferred antitumor T cells to mediate tumor regression." (PMID 31405895, 2019).
tumor (continued). "By releasing IL-1β, these cells promoted the expression of E-selectin on endothelial cells thus promoting the adhesion of tumor cells to the vascular endothelium." (PMID 31447834, 2019). "IL-1β promotes angiogenesis by activating VEGF production during tumor progression, while IL-18 suppresses angiogenesis in cancer." (PMID 31580256, 2019). "A series of cytokines and chemokines can activate STAT3 in tumor cells, among which IL-6 and IL-1β are the major inducers derived from the TME." (PMID 30927928, 2019). "CAFs are classified as tumor-restraining, tumor-promoting, secretory, or ECM-remodeling cells, which also exhibit CAF functions via mutated genes, the secreted cytokines IL-1β, TNF-α and NF-κB, inflammatory signals, epigenetic regulation, etc.." (PMID 31521169, 2019). "IL-1β plays a role in resolving acute inflammation resulting in the initiation of adaptive anti-tumor responses; however, chronic inflammatory conditions increase the risk of developing cancer." (PMID 31182982, 2019). "Secretion of IL-1β triggers Th17 differentiation and production of IL-17A which enhances neoangiogenesis and tumor recurrence." (PMID 31217433, 2019). "Accordingly, we showed that DHA-enriched diet reduces circulating IL-1β concentration and tumor recurrence in 5-FU-treated tumor-bearing mice." (PMID 31217433, 2019). "IL-1β-induced inflammation also promotes tumor development and invasiveness of 3-methylcholanthrene carcinogen-induced tumors." (PMID 31557902, 2019). "When the IL-1β dual selective antagonist was injected 1 week after tumour cell inoculation the existing bone metastases stopped growing." (PMID 31847214, 2019). "This study established a new field of application for the licensed anti-tumor drug epirubicin as an anti-inflammatory agent, reducing IL-1β and TNF-α release from macrophages when used at low-doses." (PMID 31905600, 2019). "On the other hand, in neutrophils, IL1β expression progressively increased until the 7th day, decreasing after that until the 14th day of tumor growth (albeit in this day is still higher than the first 12 h after the tumor inoculation)." (PMID 31712726, 2019). "Our data show that 4T1 tumor-bearing mice exhibit elevated expression of G-CSF and IL-1β in the tumor mass, increased neutrophil counts in the peripheral blood and elevation of indirect markers of NET formation in plasma." (PMID 31552036, 2019). "Here we show that IL-1α and IL-1β derived from tumor cells and tumor cell-conditioned macrophages is key for TSLP production by CAFs and blockade of IL-1 in vivo significantly reduced TSLP expression in the tumor." (PMID 30760333, 2019). "Mice bearing 4T1 tumor cells that ectopically express functional IL-1β or lack the IL-1 receptor antagonist exhibit increased MDSCs accumulation and their immune suppressive activity." (PMID 30998767, 2019). "In PDAC mouse models, administration of either IL-1β-neutralizing antibodies or an IRAK4 inhibitor potentiates the effect of gemcitabine in suppressing tumor growth and fibrosis." (PMID 30927908, 2019). "While beyond the scope of the current study, future generation of mice in which IL-1β will be conditionally ablated in fibroblasts will enable temporal dissection of its role during tumour progression and metastasis." (PMID 31558756, 2019). "IL1β was inhibited through systemic treatment with Anakinra, and tumour formation assessed as previously." (PMID 31676788, 2019). "Seeking to get further mechanistic insight on the role of CAF-derived IL-1β in facilitating metastatic dissemination, we investigated its effect on tumour ECs." (PMID 31558756, 2019). "We further assessed IL-1β secretion by ELISA, and found that all the different DAMPs tested and specifically tumour-derived necrotic fluid induced the secretion of IL-1β from fibroblasts." (PMID 31558756, 2019). "Cancer cells, tumor-infiltrating immune effector cells, and tumor stromal cells express IL-1α, IL-1β, and IL-1R." (PMID 31557902, 2019).